NDUFS7 (NADH:ubiquinone oxidoreductase core subunit S7)
Description:
Core subunit of the mitochondrial membrane respiratory chain NADH dehydrogenase (Complex I) which catalyzes electron transfer from NADH through the respiratory chain, using ubiquinone as an electron acceptor. Essential for the catalytic activity of complex I.
Synonyms: CI-20kD; PSST; FLJ46880; FLJ45860; CI-20; MC1DN3; MY017
Tractability: Small molecule: an approved drug acts on it; a structure with a bound ligand is known. Antibody: UniProt places it where antibodies can reach, with medium confidence. PROTAC: ubiquitination databases record sites on it; its protein half-life has been measured.
Target class: Enzyme; Oxidoreductase
Gene: Protein-coding gene on chromosome 19 (1,383,527 to 1,395,590, forward strand). Ensembl gene ENSG00000115286.
Subcellular location: Mitochondrion inner membrane
Pathways (Reactome):
Metabolism: Complex I biogenesis; Respiratory electron transport
Gene Ontology:
Molecular function: NADH dehydrogenase (ubiquinone) activity; NADH dehydrogenase activity; protein binding; oxidoreductase activity, acting on NAD(P)H, quinone or similar compound as acceptor; 4 iron, 4 sulfur cluster binding; iron-sulfur cluster binding; protease binding; quinone binding
Biological process: mitochondrial electron transport, NADH to ubiquinone; mitochondrial respiratory chain complex I assembly; aerobic respiration; electron transport coupled proton transport; proton motive force-driven mitochondrial ATP synthesis
Cellular component: mitochondrial inner membrane; mitochondrion; respiratory chain complex I; mitochondrial matrix; neuronal cell body; synaptic membrane
Genetic constraint (gnomAD): Loss-of-function variants: 11 observed, 25.08 expected, observed/expected ratio (o/e) 0.44, 90% interval 0.28 to 0.73. The upper end of that interval is the gene's LOEUF score, 0.73, which puts it in group 2 of 6, group 1 being the genes least tolerant of losing a copy. Missense variants: 263 observed, 301.04 expected, observed/expected ratio (o/e) 0.87, 90% interval 0.79 to 0.97. Synonymous variants: 136 observed, 116.99 expected, observed/expected ratio (o/e) 1.16, 90% interval 1.01 to 1.34.
Gene-disease validity (ClinGen):
ClinGen rates the evidence that NDUFS7 causes each of these diseases.
mitochondrial disease (autosomal recessive): Definitive.
Leigh syndrome (autosomal recessive): Moderate. A progressive neurological disease defined by specific neuropathological features associating brainstem and basal ganglia lesions.
Homologues: Orthologues: dog NDUFS7 (89% identical), guinea pig NDUFS7 (88% identical), mouse Ndufs7 (86% identical), macaque NDUFS7 (86% identical), chimpanzee NDUFS7 (81% identical), rat Ndufs7 (77% identical), tropical clawed frog ndufs7 (75% identical), zebrafish ndufs7 (75% identical), Drosophila melanogaster ND-20 (65% identical), Caenorhabditis elegans nduf-7 (62% identical), Drosophila melanogaster ND-20L (62% identical).
Diseases named in the same sentence as NDUFS7 in open-access papers:
NDUFS7 is named in the same sentence as 40 diseases in open-access papers, as found by Europe PMC text mining. Sharing a sentence is not in itself a finding about the gene and the disease. The quoted sentences say what the papers report.
Leigh syndrome (10 papers, 2012 to 2024). "Whole genome sequencing identified a missense variant in a gene associated with human Leigh syndrome, NDUFS7:c.535G > A or p.(Val179Met)." (PMID 38316835, 2024). "In the course of this study, the NDUFS7:p.(Val179Met) missense variant was identified in two Jack-Chi puppies with Leigh syndrome." (PMID 38316835, 2024). "Our results show the potential of the fruit fly as a model for canine disease allele validation and establish NDUFS7:p.(Val179Met) as causative variant for the investigated canine Leigh syndrome." (PMID 38316835, 2024). "Mutation of the NDUFS7 gene contributes to a complex I defect observed in some Leigh syndrome patients." (PMID 36013387, 2022). "Patients with NDUFS4 and NDUFS7 mutations almost invariably have Leigh syndrome, in patients with NDUFS7 mutations, the brainstem is often affected." (PMID 22644603, 2012). "Multiple point mutations in NDUFS7 are associated with Leigh syndrome, a heterogeneous neurological genetic disorder caused by mutations in ETC components and characterized by tell-tale brain morphology defects as well as abnormal findings in the mitochondria of skeletal muscles." (PMID 26038366, 2015). "Variants related to Complex I such as NDUFS8, NDUFS7, and NDUFA2 are found to be explanations for Leigh syndrome, a neurodegeneration showing degenerative foci in the central neural system." (PMID 36431159, 2022). "In line with previously reported complex I deficient patients, we found that defects in NDUFS7, NDUFA12, and NDUFAF5 caused Leigh-syndrome or a Leigh-like-phenotype." (PMID 30369941, 2018). "For example: Huntington’s disease (NDUFA7, NDUFC1, NDUFB2, NDUFB3, NDUFA8), atrophy of optic nerve (NDUFS4) and Leigh syndrome (NDUFS7, NDUFA2, NDUFS4)." (PMID 23028713, 2012). "Defects in NDUFS7, NDUFA12 and NDUFAF5 caused Leigh-syndrome or a Leigh-like-phenotype." (PMID 30369941, 2018).
schizophrenia (4 papers, 2014 to 2019). A major psychotic disorder characterized by abnormalities in the perception or expression of reality. "The genetic interaction for mitochondria function and schizophrenia were illustrated by DRD2 linked to NDUFS7 through protein-protein interactions of FLNA and ARRB2." (PMID 25522158, 2014). "The genetic interaction between mitochondria function and schizophrenia may be revealed by DRD2 linked to NDUFS7 through protein-protein interactions of FLNA and ARRB2." (PMID 25522158, 2014). "Paired analysis between BA24 and cerebellum reveal increases within NDUFS7 levels and mtDNA content in cerebellum of patients with bipolar disorder or schizophrenia." (PMID 31797868, 2019). "Here, we demonstrate no changes in NDUFS7 in BA24, cerebellum or hippocampus, increases in mtDNA content in hippocampus of patients with bipolar disorder, and decreases in mtDNA oxidation in patients with bipolar disorder and schizophrenia, respectively." (PMID 31797868, 2019).
breast carcinoma (2 papers, 2024 to 2025). "Thus, these analyses uncovered the possible association of the CI functionality—the NAD+‐regenerating capability accompanied by electron transfer by NDUFS1, NDUFS7, and NDUFS8—with cancer progression in patients with HR(+)/HER2(−) breast cancer." (PMID 39873399, 2025).
diabetes (2 papers, 2010 to 2023). "For instance, IGFBP2, NPAS2, NDUFS7, and TGM2 showed differential expression in α cells from individuals with T2D and have previously been shown to affect diabetes and islet-related phenotypes or mitochondrial function." (PMID 36656641, 2023). "NDUFA5, NDUFS7, SCO1 and FMO4 all are involved in oxidative phosphorylation and have been shown to be important in diabetes." (PMID 20122255, 2010).
melanoma (2 papers, 2023 to 2024). A malignant, usually aggressive tumor composed of atypical, neoplastic melanocytes. "In the view of drug targets, NDUFS4 or NDUFS7 is reported as the targeted gene by casticin or nebivolol for its role in inhibiting cell migration and invasion in mouse melanoma B16F10 cells, or in blocking complex I activity related colon and breast tumor growth, respectively." (PMID 37469574, 2023). "LONP1 over-expression results in impaired complex I assembly in melanoma cells, upregulation of NDUFB6,8,10 and 11, and downregulation of NDUFV1, NDUFV2, NDUFS3 and NDUFS7." (PMID 38263327, 2024).
atherosclerosis (1 paper, 2024). A disease characterized by the build-up of fatty material and calcium deposition in the arterial wall resulting in partial or complete occlusion of the arterial lumen. "Mitochondrial and metabolism-related genes such as NDUFS7, TMEM126B, and EIF3G were clustered together, indicating a metabolic impairment in atherosclerosis." (PMID 39120300, 2024).
glaucoma (1 paper, 2026). Increased pressure in the eyeball due to obstruction of the outflow of aqueous humor. "Collectively, these findings establish the NRF2/NDUFS7 axis as a central defense mechanism protecting TM from oxidative injury and suggest potential therapeutic strategies for glaucoma-associated ocular hypertension." (PMID 41869290, 2026).
hereditary optic neuropathy (1 paper, 2017). "Mutations in NDUFS2 and NDUFS7, orthologs of nduf-2.2/gas-1 and nduf-7, respectively, are associated with mitochondrial Complex I deficiency, which can cause hereditary optic neuropathy." (PMID 28539870, 2017).
lactic acidosis (1 paper, 2023). Metabolic acidosis characterized by the accumulation of lactate in the body. "In this present study, a proband exhibited an amino acid change from proline 144 to lysine in the NDUFS7 gene; however, he did not display any other neuromuscular symptoms or lactic acidosis typically associated with LS." (PMID 38054206, 2023).
myocardial ischemia (1 paper, 2021). A disorder of cardiac function caused by insufficient blood flow to the muscle tissue of the heart. "During myocardial ischemia/reperfusion, activation of mito-calpain results in the degradation of the NADH:ubiquinone oxidoreductase core subunit S7 (NDUFS7), a subunit essential for complex I activity, which could be prevented by the calpain inhibitor MDL-28170." (PMID 34440793, 2021).
ovarian carcinoma (1 paper, 2025). A malignant neoplasm originating from the surface ovarian epithelium. "Copy number alterations in genes such as PDCD10 and NDUFB9 (amplifications) and NDUFS7 and ZBTB7A (deletions) were also identified, particularly in ovarian cancer, suggesting their contributions to genomic instability." (PMID 40396172, 2025).
cancer (3 papers, 2022 to 2025). A tumor composed of atypical neoplastic, often pleomorphic cells that invade other tissues. "The mRNA expression of NDUFS7, linked to survival state and poor prognosis, was notably lower in cancer patients than in normal tissue, suggesting its potential utility in identifying high‐risk cancer patients." (PMID 38534098, 2024). "Mechanistically, the inhibition of the β1-adrenergic cascade in cancer cells leads to the upregulation of the mitochondrial content of ATPase inhibitory factor 1 (IF1) and also prevents the phosphorylation of Complex I subunits such as NDUFS7." (PMID 35534478, 2022).
infection (3 papers, 2020 to 2025). The state of being infected such as from the introduction of a foreign agent such as serum, vaccine, antigenic substance or organism. "Our data suggest that elevated mtROS after infection results from downregulation of SIRT3 and consequently NDUFS7 and NDUFV3." (PMID 33531400, 2021).
NDUFS7 also shares sentences with these, for which no sentence is quoted: Huntington disease (6 papers); Alzheimer disease (5); Neurological Disease (4); Parkinson disease (4); tumor (2); acute lymphoblastic leukemia (1); amyotrophic lateral sclerosis (1); bacteremia (1); bipolar disorder (1); brain diseases (1); brain ischemia (1); breast tumor (1); cervical cancer (1); colon cancer (1); Dystonia (1); frontotemporal dementia (1); inflammatory bowel disease (1); Insulin resistance (1); lathosterolosis (1); lung adenocarcinoma (1); lung carcinoma (1); malaria (1); mitochondrial myopathies (1); non-alcoholic fatty liver disease (1); ocular hypertension (1); primary carnitine deficiency (1); tuberculosis (1).